JAK2 (Janus kinase 2)
Diseases named in the same sentence as JAK2 in open-access papers (continued):
Sharing a sentence is not in itself a finding about the gene and the disease.
tumor (continued). "Brain metastatic tumor cells secrete LCN2, which binds to SLC22A17 on astrocytes, activating JAK2/STAT3 signaling and inducing astrocyte activation and chemokine secretion, thereby facilitating macrophage recruitment." (PMID 41436606, 2025). "The activation of the Janus Kinase 2/signal transducers and activators of the transcription 1 (JAK2/STAT1) signaling pathway promotes the overexpression of PD-L1 and tumor progression." (PMID 40429739, 2025). "Concurrently, C3 cleavage fragments stimulate the JAK2/STAT3 and ERK pathways, driving cellular reprogramming that promotes tumor progression." (PMID 40370471, 2025). "Mechanistically, GH action activates several oncogenic signaling cascades in NSCLC, including the JAK2/STAT5/STAT3, PI3K/AKT, and MAPK/ERK pathways, which enhance tumor cell survival, proliferation, and drug resistance in many cancers." (PMID 41515995, 2025). "Then, we compared the expression between JAK2 and NCAPD3 or STAT3 in GTEx normal tissues and TCGA tumor tissues, and found both NCAPD3 and STAT3 showed strong positive correlations with JAK2 in tumor tissues." (PMID 39917394, 2025). "It is reported that the abnormally activated JAK2/STAT3 signaling pathway enhances the occurrence and development of HCC by promoting tumor cell proliferation, migration, invasion, angiogenesis, and apoptosis inhibition." (PMID 41200213, 2025). "To further elucidate the molecular consequences of JAK2/STAT3 inhibition, we assessed the expression of downstream effectors involved in tumor proliferation, inflammation, apoptosis, and metastasis." (PMID 41200213, 2025). "Propofol can suppress cervical cancer cell viability, and enhance cisplatin-mediated apoptosis by inhibiting the EGFR/JAK2/STAT3 pathway, thereby enhancing the anti-tumor effect of cisplatin." (PMID 40309242, 2025). "JAK2/STAT3 is a classical regulatory pathway for the proliferation and apoptosis of malignant tumor cells." (PMID 41200213, 2025). "We found that tumor-derived LCN2 activated astrocytes through SLC22A17 and JAK2/STAT3 signaling, leading to the secretion of macrophage-recruiting chemokines." (PMID 41436606, 2025). "Upon binding to LepR, leptin activates the JAK2/STAT3 and PI3K/AKT signaling pathways, inducing tumor cell proliferation, EMT, and enhanced invasive capabilities." (PMID 41164182, 2025). "IL-6 and IL-1β can enhance CD274 expression in tumor cells by activating the JAK2/STAT3 signaling pathway, making it difficult to be recognized by T cells and facilitating tumor immune evasion." (PMID 39911394, 2025). "In the KOPN-49 and REH experiments, where CHZ868 demonstrated synergistic effects in the tumor rechallenge test, IFN-γ and TNF secretion was also maintained during the third tumor rechallenge, even in REH cells with wild-type JAK2." (PMID 39891728, 2025). "Compared to the model group, the mRNA expression levels of JAK2 and STAT3 in the tumor tissues of the Nolvadex group were significantly lower (P < 0.01)." (PMID 40351419, 2025). "Based on our results from the tumor and surrounding healthy tissue samples, HIF1A emerged as the primary determinant of EPO, EPOR and JAK2/STAT5A signaling pathway expression in ccRCC." (PMID 40332447, 2025). "The JAK2/STAT3 pathway plays significant roles in tumorigenesis and tumor progression across multiple cancer types." (PMID 40649917, 2025). "Sustained activation of pathways such as Janus kinase 2/signal transducer and activator of transcription 3 (JAK2/STAT3) and Toll-like receptor 4 (TLR4) promotes tumor proliferation, invasion, and metastasis." (PMID 41573719, 2025). "Mounting evidence suggests that the JAK/STAT3 signaling pathway plays a key role in tumor metastasis and EMT, with an active IL6/JAK2/STAT3 axis and stem cell‐like characteristics contributing to the poor prognosis of metastasized breast cancers." (PMID 40874680, 2025).
tumor (continued). "Given our prior findings implicating CMSP in the regulation of the JAK2/STAT3/c-Myc axis, we further focused on MYC as a potential effector mediating the anti-tumor effects of CMSP." (PMID 41347093, 2025). "Released quercetin from the quercetin‐Ferrum ion (QFN) suppresses the phosphorylation of JAK2/STAT3 and reduces PD‐L1 expression in tumor cells." (PMID 41195524, 2025). "It further drives tumor growth and reduces sorafenib sensitivity by upregulating HIF-1α and activating JAK2/STAT3 signaling." (PMID 41050691, 2025). "The subsequent Western blot analysis of tumor tissues revealed that Lyc.HCL significantly inhibited TRIM22 expression, as well as the expression of JAK2/STAT3 and ERK signaling pathway components." (PMID 40075566, 2025). "Our team recently discovered that high expression of miR-181b in HB cells promotes tumor metastasis by inhibiting the expression of SOCS2, leading to the activation of the JAK2/STAT5 signaling pathway and EMT." (PMID 41393242, 2025). "The immune escape from T cells caused by the knockout of genes IFN-γ signaling pathway (JAK1, JAK2, Ifngr2) and antigen presentation pathway (TAP1, TAP2, B2M) promotes tumor vulnerability to NK cells." (PMID 40191187, 2025). "In other words, quercetin inhibits JAK2/STAT3/PD‐L1, thereby preventing the immune escape of tumor cells." (PMID 41195524, 2025). "Icaritin inhibits the IL‐6/JAK2/STAT3 pathway by blocking the phosphorylation of JAK2 and STAT3, which suppresses downstream gene expression, prevents STAT3 nuclear translocation, and reduces tumor cell proliferation." (PMID 40035422, 2025). "TNBC cells exhibit hyperactivation of several signaling pathways, including the PI3K/Akt/mTOR, Wnt/β‐catenin, JAK2/STAT3, Ras/Raf/MEK/ERK, Notch, and Hh pathways, all of which contribute to tumor initiation and progression." (PMID 41049266, 2025). "Histological analyses of tumor tissues using IHC staining revealed that Lyc.HCL effectively reduced the expression of TRIM22 and other key signaling proteins such as JAK2 and p-AKT, further supporting its role in modulating these pathways." (PMID 40075566, 2025). "For normal spots counterfactually set to Jak2 KO normal, kNN overpredicts Plac8 (mean NEX 1.466) by inheriting signal from nearby tumor neighbors (mean NEX 1.473), thereby leaking disease-specific expression into the counterfactual." (PMID 41292874, 2025). "Among the mechanisms, one may highlight the JAK2/STAT3 signaling pathway, the activation of the extracellular-signal-regulated kinase (ERK) pathway, the upregulation of acetyl-CoA acetyltransferase 2 (ACAT2), and the induction of IL-8 expression in tumor-associated macrophages (TAMs)." (PMID 40485730, 2025). "CUR affects the STAT3 pathway in mice by significantly inhibiting tumor growth and downregulating the expression of p‐STAT3 and p‐JAK2 in tumor samples." (PMID 40860906, 2025). "Tumour cells stimulate the miR-21 expression in macrophages and suppress the activation of STAT1 and NF-κB by inhibiting STAT1 and JAK2 expression, and prevent anti-tumoural M1 polarisation." (PMID 41561520, 2025). "Specifically, CAF-derived WNT2 disrupts the JAK2/STAT3 signaling pathway, essential for maintaining DC differentiation, leading to diminished anti-tumor immunity." (PMID 40453074, 2025). "Meanwhile, deficiency of circRNA-14,052 led to a significant decrease in circRNA-14,052, IKBKB, IL-6, JAK2, and STAT3 levels, and an increase in miR-214-3p levels in tumor tissues from MCF-7 tumor-bearing mice compared to the LV-NC group." (PMID 41044672, 2025).
tumor (continued). "This thermodynamic stability is crucial for the sustained inhibition of JAK2 and PI3KCD activities, which are often upregulated in GC and contribute to tumor growth, survival, and metastasis." (PMID 39735669, 2025). "Furthermore, NGS testing identified mutations in the JAK2 and DDX3X genes in this patient, indicating that the disease is heterogeneous at the genetic level and may contribute to the malignant transformation of tumor cells." (PMID 40666527, 2025). "Since PTPRO can suppress tumour progression and metastasis by targeting STAT3 and JAK217, we focused our research on the JAK2/YAP pathway." (PMID 40016288, 2025). "The quantification of JAK2 in the HIF1A-negative tumor showed the low expression of JAK2 protein compared to control tissue; however, in the HIF1A-positive tumor, the strong expression of JAK2 was observed compared to HIF1A-negative tumor (p < 0.001)." (PMID 40332447, 2025). "This was validated by immunohistochemistry, which showed that the relative expression levels of the p-JAK2 and p-STAT3 proteins were highest in the tumor tissues of the model group." (PMID 40351419, 2025). "Abnormally expressed NCAPD3 in prostate cancer caused STAT3 to be highly expressed and bound to the promoters of JAK2 and EZH2 to promote their transcription, increasing the level of AKT phosphorylation, and accelerating tumor development." (PMID 39917394, 2025). "In conclusion, our study revealed that STA-induced inhibition of the JAK2/STAT3 pathway in macrophages can suppress TAMs M2 polarization and further inhibiting tumor cell migration and angiogenesis." (PMID 39974738, 2025). "The inhibition of the JAK2 pathway can help reverse the immunosuppressive effects within the TME, thereby improving the activity of CAR-T cells or tumor-infiltrating lymphocytes." (PMID 40486651, 2025). "The activated JAK2/STAT3 pathway is involved in the pathologies of cancer and inflammatory diseases, and it promotes carcinogenesis, tumor development, cancer cell survival, and the spread of solid tumors." (PMID 40018404, 2025). "By binding to IL6ST mRNA, miR‐224‐5p reduces IL6ST expression, suppresses the activation of the JAK2/STAT3 signaling pathway, and ultimately inhibits NSCLC cell proliferation and tumor growth." (PMID 39840666, 2025). "In cases where HIF1A is expressed, there was an upregulation of JAK2 and STAT5A proteins in tumor tissue, alongside EPOR." (PMID 40332447, 2025). "We analyzed the tumor and surrounding healthy tissue from patients with ccRCC after radical nephrectomy to explore hypoxia-related HIF1A and EPO expression and JAK2/STAT5 signaling pathways." (PMID 40332447, 2025). "CXCL11, a protective biomarker, promotes M1 macrophage polarization via JAK2/STAT1, supporting the anti-tumor role of M1 TAMs in OC." (PMID 41280929, 2025). "The aberrant activation of JAK2/STAT3 signaling has been detected across multiple solid tumors, where it drives tumorigenesis, tumor survival, proliferation, and metastatic." (PMID 40309242, 2025). "In a Tgfbr2-KO-to-distant-Jak2-KO task, kNN yields flat Plac8 predictions, whereas CONCERT reconstructs high Plac8 in the tumor core and low Plac8 at the surface, recovering the ground-truth spatial pattern." (PMID 41292874, 2025). "In vitro, RSV can exert anti-tumor effects on GBM and improve the inflammatory response in the GBM microenvironment by inhibiting the activation of the JAK2/STAT3 signaling pathway." (PMID 38546908, 2024). "The deactivation of JAK1 and JAK2 signaling resulted in the development of IFN-γ resistance, compromising immune surveillance and promoting tumor cell growth." (PMID 38785789, 2024). "CCL5 binds with a high affinity to the G-protein-coupled receptor, CCR5, which is upstream of multiple pro-tumor signaling pathways including PI3K/Akt and JAK2/STAT3." (PMID 39409924, 2024). "Qu released by QFN can decrease the expression of PD-L1 in tumor cells by inhibiting the phosphorylation of JAK2 and STAT3, thereby enhancing anti-tumor immunity." (PMID 39712006, 2024).
tumor (continued). "IL6 can reverse the SLC7A11 knockout effect through the JAK2/STAT3 pathway, inhibit ferroptosis and promote tumor resistance." (PMID 39544949, 2024). "Expression of PTPRO was negatively correlated with p-JAK2, p-STAT3, Bcl-2, and Snail levels in LUAD tumor samples." (PMID 38182570, 2024). "Abnormal expression of MUC16 promotes tumor progression through mesenchymal protein, PI3K/AKT pathway, JAK2/STAT3 pathway, ERK/FBW7/c-Myc, and other mechanisms, and plays an important role in the occurrence and development of tumors." (PMID 38758220, 2024). "CRC-regulated macrophages regulate the EMT program and enhance migration and infiltration of CRC cells by secreting IL6, which activates the JAK2/STAT3 pathway and suppresses the tumor suppressor miR-506-3p in CRC cells." (PMID 39068459, 2024). "JAK2 activation induces constitutive phosphorylation of STAT3, potentially driving neoplasm growth and metastasis." (PMID 38200372, 2024). "Aberrant activation of the JAK2/STAT3 signaling pathway deteriorates cancer progression and induces an immunosuppressive tumor microenvironment." (PMID 38686052, 2024). "As a natural small molecule inhibitor of the IL-6/JAK2/STAT3 pathway, ginsenoside Rh2 shows great potential as an anti-tumor agent." (PMID 39845783, 2024). "Consistently, in our study, we proved that PL resulted in the reduction of the p-PI3K/p-AKT/p-mTOR/JAK2/p-STAT3 and the augment of the p-p38/p-ERK1/2/p-JNK in the H22 tumor-bearing mice." (PMID 38240856, 2024). "In line with previous studies, our current research found that CXCL10 activates pro-angiogenic and pro-growth signals, such as ERK, AKT, JAK2, and CREB, potentially mediated by CXCR3-A, which lead to increased B16F10 tumor growth and angiogenesis." (PMID 39268223, 2024). "The demethylase FTO has been shown to be responsible for decreasing m6A methylation of Apolipoprotein E (APOE) mRNA and modulating the IL-6/JAK2/STAT3 signaling pathway, thereby inhibiting tumor glycolysis and abrogating tumor growth." (PMID 38902779, 2024). "The IL-6/JAK2/STAT3 pathway is involved in various biological processes, including tumor cell proliferation, apoptosis, migration, invasion, and cell cycle progression." (PMID 39845783, 2024). "These in vitro experiments suggest the Jak2 inhibitor suppresses both the autonomic synthesis and release of ACTH in corticotroph tumor cells." (PMID 38862897, 2024). "On the one hand, CHRNA5 can activate multiple signalling pathways, such as TGF-β1–Smad, JAK2/STAT3 and Notch1, thus promoting tumour cell proliferation, survival and metastasis." (PMID 38879667, 2024). "EGFR, the most prevalent molecule in the study, exhibited differential expression in CRG subgroups, contributing to tumor cell differentiation, proliferation, and migration by regulating several signaling pathways, including PI3K/AKT, RAS/MAPK, and JAK2/STAT." (PMID 38956740, 2024). "Inhibition of JAK2/STAT3 signaling induces CRC cell apoptosis and cell cycle arrest, and suppresses tumor growth and invasion in CRC." (PMID 38673975, 2024). "Previous studies reported that HHT exerts anti-tumor effects by regulating several signaling pathways, including the MEK/ERK, PI3K/AKT, and JAK2/STAT3 signaling pathway." (PMID 38770133, 2024). "Janus kinase 2 (JAK2) plays a critical role in orchestratinghematopoiesis,and its deregulation leads to various blood disorders, most importantlymyeloproliferative neoplasms (MPNs)." (PMID 38843875, 2024). "JAK2/STAT3 is a classical IL-6 signaling pathway that can promote inflammation and tumor progression." (PMID 38424624, 2024). "Proteomics investigation revealed that andrographolide inhibited JAK2/STAT3 signaling by downregulating the phosphorylation status of STAT3, which in turn decreased the expression of tumor PD-L1 in NSCLC." (PMID 38397437, 2024). "As the JAK2/p-STAT3 pathway is a classic inflammatory pathway involved in tumor progression, we subsequently explored the effects of ALKBH5 on JAK2/p-STAT3 signaling in NSCLC." (PMID 38872221, 2024).
tumor (continued). "By means of the JAK2/STAT3 signaling pathway, SIRT6 can inhibit tumor cell growth by inducing apoptosis and diminishing oxidative stress." (PMID 39408693, 2024). "Taken together, these results suggest that GP73 targets the activation of the JAK2/STAT3 pathway to stimulate HUVEC growth and migration in vitro and promotes HCC tumor angiogenesis in vivo." (PMID 38939041, 2024). "As more and more credible evidence continues to emerge, the clinical application potential of the JAK2/STAT3 therapy has also gradually garnered significant attention in the treatment of chronic pain, such as osteoarthritis (OA) and tumor pain." (PMID 37307838, 2024). "The heterodimeric IFNGR1/IFNGR2 receptor complex on tumor cells binds to IFN-γ released by tumor-specific T lymphocytes, activating JAK1 and JAK2, which subsequently phosphorylate a transcription factor known as STAT1." (PMID 38785789, 2024). "We also found the same results in tumor tissues, especially in the RSJ-H group; however, the p-Jak2/Jak2 ratio showed a decreasing trend in the RSJ-M and RSJ-H groups, although these results were not statistically different." (PMID 39203920, 2024). "TAM-derived IL-6 activated the JAK2/STAT3 pathway, and activated STAT3 inhibited transcription of the tumor suppressor miR-506-3p in CRC cells." (PMID 39199574, 2024). "The effect of a potent and selective Jak2 inhibitor, SD1029, on ACTH production and proliferation investigated in mouse AtT20 corticotroph tumor cells." (PMID 38862897, 2024). "IL-6, IL-8 have been reported to induce chemoresistance in cancer through activation of the Jak2/Stat3 signaling pathway, activation of Stat3 can further promote VEGF expression and induce tumor angiogenesis." (PMID 39193386, 2024). "Immunohistochemical experiments detected the expression of SRPK1 downstream, β-catenin, p-JAK-2, and p-STAT3 in subcutaneous tumor tissues of nude mice." (PMID 38397980, 2024). "In our current study, we gathered clinical samples of ATC, PTC, and NT tissues and established a noteworthy confirmation of the heightened expression levels of JAK1, p-JAK1, JAK2, p-JAK2, STAT3, and p-STAT3 proteins within the tumor cells of ATC patients." (PMID 38336839, 2024). "Piperlongumine, a bioactive alkaloid known for its antioxidant and anti-tumor properties, has been found to inhibit TNBC cell proliferation and migration by inhibiting JAK2/STAT3 pathway phosphorylation." (PMID 38699644, 2024). "In CC cases with heterogeneous EMR1 expression, specific JAK-STAT genes (JAK2, JAK3, STAT1, STAT2, and STAT3) were upregulated in the EMR1-H/L ROI compared to those in the EMR1-N ROI within the same tumor." (PMID 38673975, 2024). "Tumor cells promote CAF generation, and the CAFs, in turn, improve the invasiveness and metastasis of the malignant T cells through the IL-6/JAK2/STAT3/SOX4 or IL-6/HIF-1α/SOX4 pathway." (PMID 39963655, 2024). "DENRKO has been reported to impair JAK2 translation and subsequent responses to IFN-γ in mouse tumor cells." (PMID 37875108, 2023). "By persistently stimulating the signaling pathway of JAK2/STAT3, which is m6A-dependent, upregulation of the ALKBH5-HOXA10 loop enhances EOC tumor development and cisplatin resistance." (PMID 36831377, 2023). "This modification was revealed to be pivotal for various key aspects of STAT3 signaling, including its cellular membrane localization, interaction with JAK2, Y705 phosphorylation, and ultimately, PRMT6-mediated tumor metastasis." (PMID 37813837, 2023). "JAK2 plays a major role in growth factor signaling and histone modifications, while TSC2 is a tumor suppressor that inhibits cell growth by downregulating the mTORC1 pathway." (PMID 38137511, 2023). "A study has found that exosomes can activate the JAK2/PI3K/Akt pathway by targeting CBLB, promote macrophage polarization to the M2 phenotype, and subsequently promote tumor progression." (PMID 37781198, 2023).